TENT4A (terminal nucleotidyltransferase 4A)
Description:
Terminal nucleotidyltransferase that catalyzes preferentially the transfer of ATP and GTP on RNA 3' poly(A) tail creating a heterogeneous 3' poly(A) tail leading to mRNAs stabilization by protecting mRNAs from active deadenylation. Also functions as a catalytic subunit of a TRAMP-like complex which has a poly(A) RNA polymerase activity and is involved in a post-transcriptional quality control mechanism. Polyadenylation with short oligo(A) tails is required for the degradative activity of the exosome on several of its nuclear RNA substrates. Has no terminal uridylyltransferase activity, and does not play a role in replication-dependent histone mRNA degradation via uridylation.
Synonyms: TRF4-1; PAPD7; POLS; TRF4; POLK; LAK-1; LAK1; TRF41; TUTASE5
Tractability: PROTAC: ubiquitination databases record sites on it.
Target class: Enzyme; Transferase
Gene: Protein-coding gene on chromosome 5 (6,713,291 to 6,757,045, forward strand). Ensembl gene ENSG00000112941.
Subcellular location: Cytoplasm; Nucleus, nucleoplasm
Subcellular location (Human Protein Atlas): Nucleoplasm; Golgi apparatus; Nuclear membrane
Pathways (Reactome):
Disease: Signaling by BRAF and RAF1 fusions
Metabolism of RNA: Nuclear RNA decay
Gene Ontology:
Molecular function: guanylyltransferase activity; protein binding; adenylyltransferase activity; poly(A) RNA polymerase activity; SMC family protein binding
Biological process: negative regulation of nuclear-transcribed mRNA poly(A) tail shortening; positive regulation of 3'-UTR-mediated mRNA stabilization; response to xenobiotic stimulus; double-strand break repair; mitotic chromosome condensation; polyadenylation-dependent ncRNA catabolic process; RNA 3'-end processing; RNA catabolic process; sister chromatid cohesion
Cellular component: cytoplasm; nucleoplasm; nucleus; nucleolus; TRAMP complex
Genetic constraint (gnomAD): Loss-of-function variants: 5 observed, 50.43 expected, observed/expected ratio (o/e) 0.0991, 90% interval 0.051 to 0.21. The upper end of that interval is the gene's LOEUF score, 0.21, which puts it in group 1 of 6, group 1 being the genes least tolerant of losing a copy. Missense variants: 696 observed, 809.98 expected, observed/expected ratio (o/e) 0.86, 90% interval 0.81 to 0.92. Synonymous variants: 380 observed, 337.86 expected, observed/expected ratio (o/e) 1.12, 90% interval 1.03 to 1.22.
Homologues: Orthologues: macaque TENT4A (99% identical), dog TENT4A (93% identical), chimpanzee TENT4A (93% identical), mouse Tent4a (92% identical), rat Tent4a (92% identical), guinea pig TENT4A (73% identical), rabbit TENT4A (65% identical), pig TENT4A (62% identical), zebrafish tent4a (49% identical), Drosophila melanogaster Trf4-1 (38% identical), Caenorhabditis elegans gld-4 (24% identical), Drosophila melanogaster Trf4-2 (20% identical). Paralogues in human: TENT4B (42% identical).
Diseases named in the same sentence as TENT4A in open-access papers:
TENT4A is named in the same sentence as 18 diseases in open-access papers, as found by Europe PMC text mining. Sharing a sentence is not in itself a finding about the gene and the disease. The quoted sentences say what the papers report.
endometrial cancer (2 papers, 2021 to 2023). Primary or metastatic malignant neoplasm involving the endometrium (mucous membrane that lines the endometrial cavity). "HOXD-AS2 could promote glioblastoma cell proliferation, migration and invasion by regulating the miR-3681–5p/MALT1 signaling pathway, TENT4A indirectly regulatesRAD18 via the tumor suppressor CYLD and via PAXIP1-AS2 in endometrial cancer." (PMID 36911393, 2023).
cervical cancer (1 paper, 2025). A primary or metastatic malignant neoplasm involving the cervix. "Additionally, human papilloma virus (HPV)-induced cervical cancer is associated with the downregulation of TUT7/ZCCHC6 and the upregulation of TENT2/PAPD4/GLD2 and TENT4A/PAPD7, although the impact of these changes on miRNA 3′ tailing remains to be determined." (PMID 40243428, 2025).
leukemia (1 paper, 2026). A malignant (clonal) hematologic disorder, involving hematopoietic stem cells and characterized by the presence of primitive or atypical myeloid or lymphoid cells in the bone marrow and the blood. "Furthermore, our results also suggest that in leukemia cells, TENT4A, TENT5A, TENT5B, TENT5C, TENT5D, and TUT1 may mediate the non-templated nucleotide additions to the 3'ends of miRNAs." (PMID 42038404, 2026).
infection (2 papers, 2016 to 2025). The state of being infected such as from the introduction of a foreign agent such as serum, vaccine, antigenic substance or organism. "Accordingly, in vitro transcribed hsRNAs with a 30 nt 3′ poly(A) tail were transfected into wildtype, ZCCHC14-depleted (ZCCHC14-KO), or TENT4A/B-depleted (TENT4A/B-KO) Huh-7.5 cells, and this was followed by infection with the 18f-NLuc reporter virus for 72 h." (PMID 40431677, 2025).
TENT4A also shares sentences with these, for which no sentence is quoted: tumor (4 papers); cancer (2); breast carcinoma (1); Cerebellar hypoplasia (1); COVID-19 (1); experimental autoimmune encephalomyelitis (1); glioblastoma (1); Hepatitis (1); hypospadias (1); lymphoma (1); oral cancer (1); periodontitis (1); Thyroid Carcinoma (1); uterine corpus endometrial carcinoma (1).